WNT5A (Wnt family member 5A)
Description:
Ligand for members of the frizzled family of seven transmembrane receptors. Can activate or inhibit canonical Wnt signaling, depending on receptor context. In the presence of FZD4, activates beta-catenin signaling. In the presence of ROR2, inhibits the canonical Wnt pathway by promoting beta-catenin degradation through a GSK3-independent pathway which involves down-regulation of beta-catenin-induced reporter gene expression (By similarity). Suppression of the canonical pathway allows chondrogenesis to occur and inhibits tumor formation. Stimulates cell migration. Decreases proliferation, migration, invasiveness and clonogenicity of carcinoma cells and may act as a tumor suppressor. Mediates motility of melanoma cells. Required during embryogenesis for extension of the primary anterior-posterior axis and for outgrowth of limbs and the genital tubercle. Inhibits type II collagen expression in chondrocytes (By similarity).
Synonyms: hWNT5A
Tractability: Antibody: UniProt places it where antibodies can reach, with high confidence; its Gene Ontology location is reachable by antibodies, with high confidence; UniProt predicts a signal peptide or a membrane-spanning region. PROTAC: ubiquitination databases record sites on it.
Gene: Protein-coding gene on chromosome 3 (55,465,715 to 55,490,539, reverse strand). Ensembl gene ENSG00000114251.
Subcellular location: Secreted, extracellular space, extracellular matrix; Secreted
Subcellular location (Human Protein Atlas): Microtubules; Mitotic spindle; Primary cilium; Nucleoli fibrillar center; Predicted to be secreted
Pathways (Reactome):
Signal Transduction: Asymmetric localization of PCP proteins; Ca2+ pathway; Class B/2 (Secretin family receptors); Negative regulation of TCF-dependent signaling by WNT ligand antagonists; PCP/CE pathway; TCF dependent signaling in response to WNT; WNT ligand biogenesis and trafficking; WNT5A-dependent internalization of FZD2, FZD5 and ROR2; WNT5A-dependent internalization of FZD4
Vesicle-mediated transport: Cargo recognition for clathrin-mediated endocytosis; Clathrin-mediated endocytosis
Disease: WNT5:FZD7-mediated leishmania damping
Gene Ontology:
Molecular function: frizzled binding; protein binding; receptor tyrosine kinase-like orphan receptor binding; cytokine activity; phospholipid binding; receptor ligand activity; chemoattractant activity involved in axon guidance; protein domain specific binding; signaling receptor binding
Biological process: cellular response to calcium ion; cellular response to lipopolysaccharide; cellular response to transforming growth factor beta stimulus; cellular response to type II interferon; embryonic skeletal system development; epithelial to mesenchymal transition; face development; genitalia development; hematopoietic stem cell proliferation; inflammatory response; intracellular protein localization; keratinocyte differentiation; macrophage derived foam cell differentiation; male gonad development; negative regulation of apoptotic process; negative regulation of canonical Wnt signaling pathway; negative regulation of DNA-templated transcription; negative regulation of fat cell differentiation; negative regulation of mesenchymal cell proliferation; phospholipase C-activating G protein-coupled receptor signaling pathway; positive regulation of angiogenesis; positive regulation of chemokine production; positive regulation of cytokine production involved in immune response; positive regulation of DNA-templated transcription; positive regulation of endothelial cell migration; and 71 more
Cellular component: extracellular matrix; extracellular region; glutamatergic synapse; clathrin-coated endocytic vesicle membrane; endocytic vesicle membrane; endoplasmic reticulum lumen; extracellular exosome; Golgi lumen; plasma membrane; cell surface; postsynapse; Schaffer collateral - CA1 synapse
Genetic constraint (gnomAD): Loss-of-function variants: 9 observed, 35.96 expected, observed/expected ratio (o/e) 0.25, 90% interval 0.15 to 0.44. The upper end of that interval is the gene's LOEUF score, 0.44, which puts it in group 1 of 6, group 1 being the genes least tolerant of losing a copy. Missense variants: 426 observed, 502.38 expected, observed/expected ratio (o/e) 0.85, 90% interval 0.78 to 0.92. Synonymous variants: 210 observed, 201.25 expected, observed/expected ratio (o/e) 1.04, 90% interval 0.93 to 1.17.
Gene-disease validity (ClinGen):
ClinGen rates the evidence that WNT5A causes each of these diseases.
autosomal dominant Robinow syndrome (autosomal dominant): Moderate. Autosomal dominant Robinow syndrome (DRS) is the more common type of Robinow syndrome (RS) characterized by mild to moderate limb shortening and abnormalities of the head, face and external genitalia.
Homologues: Orthologues: chimpanzee WNT5A (99% identical), dog WNT5A (99% identical), pig WNT5A (99% identical), rabbit WNT5A (99% identical), guinea pig WNT5A (99% identical), mouse Wnt5a (99% identical), macaque WNT5A (98% identical), rat Wnt5a (98% identical), tropical clawed frog wnt5a (84% identical), zebrafish wnt5a (72% identical), Drosophila melanogaster Wnt5 (44% identical), Caenorhabditis elegans cwn-2 (40% identical), and 4 more. Paralogues in human: WNT5B (76% identical), WNT2B (47% identical), WNT2 (45% identical), WNT4 (43% identical), WNT3A (42% identical), WNT3 (42% identical), WNT7B (41% identical), WNT7A (40% identical), WNT10A (38% identical), WNT6 (38% identical), WNT1 (38% identical), WNT16 (37% identical), and 6 more.
Diseases named in the same sentence as WNT5A in open-access papers:
WNT5A is named in the same sentence as 384 diseases in open-access papers, as found by Europe PMC text mining. Sharing a sentence is not in itself a finding about the gene and the disease. The quoted sentences say what the papers report.
melanoma (231 papers, 2005 to 2025). A malignant, usually aggressive tumor composed of atypical, neoplastic melanocytes. "Wnt5a promotes the aggressiveness of melanoma by stimulating the release of SEVs, enhancing the risk of metastasis." (PMID 38243280, 2024). "As cJUN activity defines the MITFlow transcriptome, factors such as Wnt5a, which can activate cJUN, are associated with the dedifferentiated melanoma state." (PMID 37043573, 2023). "Further studies suggested a phenotypic switch model of melanoma cells, in which the expression of WNT5A and CTNNB1 (encodes β-catenin) dictates the proliferation or invasion status." (PMID 36620565, 2022). "We then analyzed invasion using the 3D spheroid invasion method and observed that knockdown of WNT5A caused a significant decrease in the invasion of both melanoma cell lines." (PMID 33969605, 2021). "The mechanism underlying our novel observation that WNT5A knockdown in these melanoma cells triggers a counteracting feedback response is a switch in RND3‐RhoA signaling." (PMID 33969605, 2021). "The association between elevated expressed WNT5A and progression of melanoma and lung cancer, breast cancer, and prostate cancer was reported." (PMID 34178988, 2021). "Lower proliferation of RNF43/ZNRF3 dKO cells can be caused by senescence because these cells have elevated WNT5A pathway activity (i.e.) and WNT5A at the same time causes a senescence-like phenotype of melanoma after exposition to vemurafenib." (PMID 34702444, 2021). "The myeloid-specific Wnt5a deletion led to a decreased level of tumor growth in a mouse melanoma model, associated with diminished levels of intra-tumoral MDSC and Treg infiltration." (PMID 34831183, 2021). "Increased expression of cytoplasmic Wnt5A has been associated with melanoma progression and poor outcomes." (PMID 33578751, 2021). "Ultimately, RNF43 overexpression here efficiently suppressed all tested pro-metastatic properties of melanoma cells associated with WNT5A and its (co)receptors." (PMID 34702444, 2021). "Aberrant WNT5A expression has been implicated not only in melanoma progression but also in the progression of a number of other cancers." (PMID 33969605, 2021). "Knocking down autophagy-related gene 5 (ATG5) in WNT5Ahigh melanoma cells caused a reduction of the WNT5A level and induction of β-catenin." (PMID 32659938, 2020). "Analyses of melanoma patient databases suggested that similar to WNT5A expression, MARCKS expression appears to be associated with increased metastasis." (PMID 32033033, 2020). "Pro-metastatic effects of WNT5A have been associated with aerobic glycolysis promoted by WNT5A in melanoma cells." (PMID 32659938, 2020). "When BRAFi‐R melanoma cells were exposed separately to either an IL‐6 Ab or the WNT5A antagonist Box5, it caused, in both cases, impaired invasive migration of these cells." (PMID 30582770, 2019). "In fact, aerobic glycolysis has been associated with the function of WNT5A in melanoma cells, and this activity has been related to an increase in active Akt signaling and high lactate dehydrogenase (LDH) levels in the serum." (PMID 30166456, 2018). "Wnt5a has been implicated in melanoma progression and metastasis, although the exact downstream signaling events that contribute to melanoma metastasis are poorly understood." (PMID 29648538, 2018). "Upregulation of WNT5A is associated with breast cancer, prostate cancer, melanoma and pancreatic cancer, indicating its oncogenic role in these cancers." (PMID 29882812, 2018). "In the adult, overproduction of Wnt5a has been commonly associated with tumor growth such as human melanoma and breast, pancreatic and gastric cancer." (PMID 28469167, 2017).
melanoma (continued). "For example, Fzd5/Wnt5a activates the Ca2+ pathway in melanoma and is associated with a more aggressive phenotype, whilst in the developing retina Fzd5 signals via β-catenin." (PMID 27196929, 2016). "As previously demonstrated, extracted data revealed that significantly increased mRNA expression of WNT5A is associated with an invasive phenotype signature of melanoma cells." (PMID 27191257, 2016). "WNT-5A also suppresses expression of tumor-associated antigens in melanoma cells via activation of PKC and STAT3." (PMID 26514730, 2016). "Increased WNT5A expression is associated with a higher invasive and metastatic potential of melanoma cells." (PMID 27191257, 2016). "There is also evidence that increased WNT5A expression is associated with cancer progression and with the movement and invasiveness of melanoma cells." (PMID 25823923, 2015). "We have demonstrated that the WNT5A antagonistic peptide Box-5 (a t-butyloxycarbonyl-modified WNT5A-derived hexapeptide) caused a significant inhibition of WNT5A-stimulated A2058 melanoma cell migration." (PMID 26393652, 2015). "We will also discuss the basis of melanoma disease, the signaling pathways associated with melanoma progression, and WNT5A signaling intervention as a new approach for future combinatorial therapy for malignant melanoma." (PMID 26393652, 2015). "An early study of gene expression profiling found that Wnt5a/PKC signaling was associated with aggressive melanoma behavior." (PMID 24944588, 2014). "In support of a role of Wnt5a in cell migration, Wnt5a has been associated with migration ability in melanoma." (PMID 23947922, 2013). "On the other hand, a tumor promoting function has been strongly documented for Wnt-5a in melanoma and in melanoma elevated Wnt-5a expression has also been associated with poor prognosis." (PMID 23990917, 2013). "For instance, a decade ago global transcriptional profiling suggested that over-expression of WNT5A denoted a highly aggressive melanoma phenotype associated with enhanced cellular motility." (PMID 22537248, 2012). "Both tyrosine kinase receptors function in the development of multiple tissues as well as cancer; cKit is a proto-oncogene implicated in melanoma and gastrointestinal stromal tumors, and Wnt5a expression has been correlated with tumor invasiveness." (PMID 22216013, 2011). "FZD5 was down-regulated in response to differentiation of NT2/D1 cells and in human melanoma cells FZD5 activation by WNT5A had been associated with elevated metastatic potential." (PMID 19874621, 2009). "Moreover, overexpression of Wnt Family Member 5A (WNT5A) in several melanoma cell lines was associated with increased release of exosomes enriched in VEGF, IL-6, IL-8, and MMP-2." (PMID 39866233, 2025). "To analyze whether impaired Cdc42 signaling is responsible for the reduced invasion caused by WNT5A knockdown in these melanoma cells, we stimulated the cells with a Cdc42 and Rac1 activator." (PMID 33969605, 2021). "In turn, downregulation of ATG5 in WNT5ahigh melanoma cells was associated with lower level of WNT5a and increased level of β-catenin, supporting the conclusion that autophagy is inversely correlated with the activity of canonical WNT/β-catenin signaling pathway." (PMID 32340261, 2020). "In addition, loss of Klotho leads to increased Wnt5A expression, filamin cleavage, and cell migratory potential during melanoma progression." (PMID 32614356, 2020). "However, Wnt5a has also been implicated in impairing dendritic cell functions and creating an immune suppressive environment in a mouse melanoma model." (PMID 31781093, 2019). "Furthermore, an IL‐6/WNT5A positive feedback loop has been previously shown to be associated with the increased invasive migration of parental BRAFi‐sensitive melanoma cells." (PMID 30582770, 2019). "In melanoma, Wnt5a was associated with the release of IL-6, VEGF, and MMP2." (PMID 31510045, 2019).
melanoma (continued). "High levels of WNT5A has been implicated in poor prognosis in advanced melanoma patients, and may hypothetically be related to stimulation of exosomal release." (PMID 28796150, 2017). "In addition to MAPK-ERK, PI3K-AKT and EGFR signaling, WNT5A signaling has also been implicated in melanoma resistance to BRAFi therapy." (PMID 26393652, 2015). "We looked at factors associated with the RISC pathway that may regulate Wnt5a levels during melanoma progression." (PMID 26029828, 2015). "Indeed, further in silico gene expression analysis has revealed a significant association between Wnt5a and Foxp3 gene expression levels in human melanomas." (PMID 25339948, 2014). "Not surprisingly given its role as regulator of cell migration into adjacent tissue, the unregulated activation of Wnt5a has been associated with invasiveness and in several tumor types, including melanoma, breast cancer, gastric cancer, pancreatic cancer, and osteosarcoma." (PMID 22384081, 2012). "Knockouts of Wnt signal transduction components, including Wnt5A, can result in proliferative failure while up-regulation of Wnt5A mRNA expression been associated with a range of cancer types, including breast, lung, prostate and malignant melanomas." (PMID 17173689, 2006). "Moreover, research indicates that melanoma resistance to chemotherapy may be associated with autophagy induction triggered by Wnt5A expression." (PMID 39329721, 2024). "WNT5A has been associated with increased resistance to chemotherapeutics in ovarian and breast cancer cells, and approaches of directly targeting WNT5A-mediated signaling for cancer therapy have been proposed for prostate cancer, small cell lung cancer and melanoma." (PMID 37815464, 2023). "In the co-culture of CAAs and melanoma cells, dedifferentiation of adipocytes towards fibroblast-like phenotype (higher expression of collagen, MMPs, and α-SMA) is observed and such modified adipocytes promote melanoma cell migration through the Wnt5a pathway." (PMID 40136652, 2025). "RNF43 overexpression abrogates the Wnt5A-induced drug resistance and tumor progression and improves the OS in patients with melanoma." (PMID 41487817, 2025). "Data from the literature already highlights the potential of WNT5A downregulation to reduce melanoma’s invasive properties." (PMID 41465101, 2025). "Rosiglitazone inhibits melanoma resistance by increasing serum levels of klotho and decreasing levels of Wnt5A in the blood and tumor microenvironment of mice." (PMID 40134808, 2025). "Wnt5a activation induces an invasive phenotype in melanoma by promoting SNAIL-mediated downregulation of E-cadherin, thus facilitating EMT during tumor progression." (PMID 40399946, 2025). "Western blot analysis showed that EUE treatment under 1.5 mM H2O2 stress increased the expression of MITF, TYR, β-catenin, GSK-3β, p-GSK-3β, and Wnt-5a in B16 melanoma cells." (PMID 41496855, 2025). "Increased Wnt ligand 5a (Wnt5a) in melanoma was correlated with increased invasiveness, cell motility and changes in morphology through changes in calcium signaling." (PMID 40028182, 2025). "In melanoma, Wnt5a promotes tumor cell proliferation by activating ADP-ribosylation factor 6 (ARF6) through interaction with FZD4 or LRP6, which in turn facilitates β-catenin nuclear translocation." (PMID 40399946, 2025). "In BRAF-mutant melanomas, Wnt5a overexpression drives stromal fibrosis and DC tolerization, creating an immune-excluded TME." (PMID 40861441, 2025). "In melanoma, Wnt5a signaling phosphorylates APT1, enhancing its depalmitoylation activity while reducing dimerization." (PMID 40977744, 2025). "Previous studies have shown that melanoma cells with Wnt5a knockdown secrete lower levels of IL-6 compared to control cells 30, and activation of Wnt5a signaling in these cells enhanced IL-6 expression." (PMID 39440046, 2024). "This Wnt5A/ROR2 signalling cascade promotes filamin cleavage by calpain 1 which in turn leads to increased melanoma cell motility." (PMID 38958472, 2024).